ALDH18A1 (aldehyde dehydrogenase 18 family member A1)
Description:
Bifunctional enzyme that converts glutamate to glutamate 5-semialdehyde, an intermediate in the biosynthesis of proline, ornithine and arginine.
Synonyms: P5CS; GSAS; PYCS; ADCL3; ARCL3A; SPG9; SPG9A; SPG9B
Tractability: PROTAC: ubiquitination databases record sites on it; its protein half-life has been measured.
Target class: Enzyme; Oxidoreductase
Gene: Protein-coding gene on chromosome 10 (95,605,937 to 95,656,841, reverse strand). Ensembl gene ENSG00000059573.
Subcellular location: Mitochondrion; Mitochondrion matrix
Subcellular location (Human Protein Atlas): Mitochondria
Pathways (Reactome):
Metabolism: Glutamate and glutamine metabolism
Metabolism of proteins: Mitochondrial protein degradation
Gene Ontology:
Molecular function: glutamate 5-kinase activity; glutamate-5-semialdehyde dehydrogenase activity; identical protein binding; protein binding; RNA binding; ATP binding; catalytic activity; delta1-pyrroline-5-carboxylate synthetase activity; kinase activity; oxidoreductase activity
Biological process: citrulline biosynthetic process; glutamate metabolic process; L-proline biosynthetic process; ornithine biosynthetic process; amino acid biosynthetic process; L-glutamate catabolic process; L-glutamine catabolic process; response to temperature stimulus
Cellular component: mitochondrial matrix; mitochondrion; mitochondrial inner membrane; cytoplasm; mitochondrial membrane
Genetic constraint (gnomAD): Loss-of-function variants: 44 observed, 91.65 expected, observed/expected ratio (o/e) 0.48, 90% interval 0.38 to 0.62. The upper end of that interval is the gene's LOEUF score, 0.62, which puts it in group 2 of 6, group 1 being the genes least tolerant of losing a copy. Missense variants: 782 observed, 1,058.1 expected, observed/expected ratio (o/e) 0.74, 90% interval 0.7 to 0.78. Synonymous variants: 331 observed, 391.1 expected, observed/expected ratio (o/e) 0.85, 90% interval 0.77 to 0.93.
Gene-disease validity (ClinGen):
ClinGen rates the evidence that ALDH18A1 causes each of these diseases.
P5CS deficiency (semidominant): Definitive. An inborn error of proline/orinthine metabolism that covers a wide spectrum of phenotypes and is caused by pathogenic variants in the aldehyde dehydrogenase 18 family member A1 (ALDH18A1) gene.
Homologues: Orthologues: chimpanzee ALDH18A1 (100% identical), macaque ALDH18A1 (99% identical), pig ALDH18A1 (97% identical), dog ALDH18A1 (97% identical), rabbit ALDH18A1 (97% identical), guinea pig ALDH18A1 (96% identical), mouse Aldh18a1 (95% identical), rat Aldh18a1 (95% identical), tropical clawed frog aldh18a1 (87% identical), Drosophila melanogaster P5CS (55% identical), Caenorhabditis elegans alh-13 (52% identical).
Diseases named in the same sentence as ALDH18A1 in open-access papers:
ALDH18A1 is named in the same sentence as 87 diseases in open-access papers, as found by Europe PMC text mining. Sharing a sentence is not in itself a finding about the gene and the disease. The quoted sentences say what the papers report.
cutis laxa (12 papers, 2015 to 2025). Cutis laxa (CL) is an inherited or acquired connective tissue disorder characterized by wrinkled, redundant and sagging inelastic skin associated with skeletal and developmental anomalies and, in some cases, with severe systemic involvement. "De novo mutation of ALDH18A1 associated with ADCL type 3 has been found to be the mildest subtype of cutis laxa with mostly skin and joint findings and hardly any associated pulmonary or cardiovascular comorbidities, as are seen with type 1 and type 2 ADCL." (PMID 40018427, 2025). "Mutations in the ALDH18A1 gene have been associated with certain diseases, such as cutis laxa and spastic paraplegia." (PMID 39350574, 2024). "ALDH18A1 mutations have previously been shown to cause autosomal dominant and recessive forms of Cutis Laxa." (PMID 39480826, 2024). "A variant in ALDH18A1 has been found to reduce cellular arginine, and dietary arginine supplementation of a cutis laxa patient carrying this variant has been shown to attenuate disease symptoms." (PMID 36561772, 2022). "Variants in ALDH18A1 have been reported to cause cutis laxa, a rare connective tissue disorder associated with abnormal ECM." (PMID 36561772, 2022). "Mutations in ALDH18A1 can cause forms of cutis laxa, inherited as autosomal dominant (AD3, MIM#616603) or autosomal recessive (ARIIIA, MIM#219150) disease." (PMID 30853934, 2019). "Homozygous mutations in ALDH18A1 (or other genes e. g., PYCR1, ATP6V0A2) can result in a heteogenous group of rare diseases characterized by loose or wrinkly skin known as cutis laxa." (PMID 26569114, 2015).
melanoma (12 papers, 2012 to 2024). A malignant, usually aggressive tumor composed of atypical, neoplastic melanocytes. "ALDH18A1, the gene encoding pyrroline-5-carboxylate synthase (P5CS), has been implicated in both breast cancer and melanoma, and mutations in ALDH18A1 can cause cutaneous phenotypes including loose skin with low elasticity." (PMID 38761252, 2024). "An inhibition of the gene ALDH18A1 encoding pyrroline-5-carboxylate synthase regulating proline biosynthesis in melanoma cells significantly decreased cultured melanoma cell viability and tumour growth." (PMID 35216552, 2022). "Increased protein synthesis is a key process in melanoma, which is regulated by the ALDH18A1 gene encoding pyrroline-5-carboxylate synthase (P5CS)." (PMID 32637352, 2020). "Nevertheless, the identification of ALDH18A1 encoding P5CS as a critical gene for melanoma viability and growth was an important finding." (PMID 28990419, 2019). "The inhibition of ALDH18A1 can inhibit cancer growth by 60% to 99% and reduce the viability of melanoma cells by 90%, whereas exogenous supplementation with proline can reverse this effect." (PMID 39051546, 2024). "ALDH18A1 knockdown decreases intracellular proline levels and impairs melanoma cell viability and tumor progression." (PMID 36694633, 2023). "ALDH18A1 overexpression locks melanoma cells into a more proliferative or tumorigenic state via proline biosynthesis." (PMID 36694633, 2023). "We have previously reported that targeting proline biosynthesis, through siRNA knockdown of ALDH18A1, is capable of significantly inhibiting melanoma cell and xenograft tumor growth." (PMID 32637352, 2020). "Knockdown of ALDH18A1 protein levels has been shown to significantly decrease melanoma cell viability and tumor growth, leading to eIF2α phosphorylation through GCN2 activation." (PMID 32637352, 2020). "P5CS is involved in proline biosynthesis and targeting ALDH18A1 has previously been shown to inhibit melanoma development by decreasing intracellular proline levels to increase the phosphorylation of eIF2α mediated by GCN2, which then impairs mRNA translation." (PMID 32637352, 2020). "In addition, ALDH18A1 seems to play an important role in melanoma growth through the proline biosynthesis pathway, because when it was knockdowned by siRNA, melanoma cell and xenograft tumor growth was inhibited." (PMID 37686694, 2023). "Thus, the proline synthesis pathway can be therapeutically targeted by inhibiting ALDH18A1 in melanoma." (PMID 36694633, 2023). "Thus, targeting the protein production with Sal and 4E1RCat effectively impaired melanoma viability and could be used to target melanoma cells having high levels of ALDH18A1." (PMID 32637352, 2020). "ALDH18A1 affects proline metabolism and thus regulates protein synthesis through GCN2 and eIF2a and thereby melanoma cell proliferation." (PMID 39051546, 2024). "By targeting ALDH18A1, GCN2-mediated phosphorylation of eIF2α is increased by decreasing intracellular proline levels, thereby inhibiting the development of melanoma." (PMID 34970420, 2021). "Moreover, ALDH18A1 knock-down activates AAR stress signaling, and reduces melanoma tumor growth both in vitro and in vivo, whereas PYCR1 induction improves proliferation and invasiveness of breast, esophagus, lung, melanoma, pancreas, and prostate cancer cells." (PMID 34458276, 2021).
hepatocellular carcinoma (11 papers, 2019 to 2025). A malignant tumor that arises from hepatocytes. "Aldh18a1, a key player in proline biosynthesis, drives hepatocellular carcinoma cell proliferation yet remains low in normal tissues." (PMID 40941077, 2025). "ALDH18A1 is capable of regulating cell proliferation in hepatocellular carcinoma by modifying the pentose phosphate pathway." (PMID 39051546, 2024). "It has been found that the proline biosynthesis pathway contributes to the growth of hepatocellular carcinoma tumors, and Aldh18a1 is one of the targets of the proline biosynthesis pathway, promoting the proliferation of hepatocellular carcinoma cells." (PMID 38998524, 2024). "ALDH18A1 affects the stability of HIF1α by regulating the level of proline metabolism and thereby regulates the proliferation of hepatocellular carcinoma cells." (PMID 39051546, 2024). "They showed that hypoxic microenvironments activated proline metabolism via upregulation of ALDH18A1 in tumor samples from patients with hepatocellular carcinoma." (PMID 31088535, 2019). "Thus, ALDH18A1 promotes hepatocellular carcinoma cell proliferation, and inhibition of ALDH18A1 may be a novel therapeutic strategy for hepatocellular carcinoma." (PMID 39051546, 2024). "The Cancer Genome Atlas (TCGA) database and gene expression profiles from a Singapore-based cohort reveal that PYCR1 and ALDH18A1 are among the most up-regulated genes in Hepatocellular Carcinoma (HCC)." (PMID 32500033, 2020). "Similarly, ALDH18A1, a key enzyme in the de novo synthesis of proline and arginine, plays a crucial role in tumor metabolic reprogramming, Previous studies have shown that ALDH18A1 promotes the proliferation of hepatocellular carcinoma by influencing glycolysis and the pentose phosphate pathway." (PMID 41573681, 2025). "Other findings have reported that the expression of the P5CS gene ALDH18A1 is increased and contributes toward enhanced L-proline biosynthesis in fibroblasts stimulated with TGF-β and in hepatocellular carcinoma cells subject to hypoxic environment." (PMID 33083024, 2020). "In addition, knockdown of MYC significantly reduces proline and hydroxyproline production in hepatocellular carcinoma cells under hypoxic conditions, indicating that the glutamine metabolic axis via MYC/GLS and MYC/ALDH18A1 is essential for proline synthesis under hypoxic conditions." (PMID 39051546, 2024).
breast carcinoma (9 papers, 2020 to 2025). "Higher ALDH18A1 expression is observed in ER+HER2high (luminal B) breast cancers compared with ER+HER2low (luminal A) breast cancers and is strongly associated with poor patient prognosis." (PMID 39051546, 2024). "ALDH18A1 is overexpressed in highly proliferative luminal B compared to low proliferative luminal A breast cancer subtypes." (PMID 36694633, 2023). "Proteomic analysis showed that PYCR1, PYCR2 and P5C synthase (P5CS/ALDH18A1) are all elevated in breast cancer patients’ samples." (PMID 37046596, 2023). "Furthermore, high protein expression of glutamine-prolinases (GLS, ALDH18A1 and P5CR) is associated with high c-Myc protein expression in only luminal B breast cancer, suggesting that c-Myc is the driving force behind the metabolic state of the breast cancer subclass." (PMID 39051546, 2024). "Furthermore, the knockdown or inhibition of ALDH18A1 in luminal B breast cancer may contribute to the therapeutic effects resulting from targeting this enzyme." (PMID 39051546, 2024). "In Breast Cancer (BC) tumors, PYCR1 and ALDH18A1 expression levels varies among specific BC subtype." (PMID 32500033, 2020). "ALDH18A1 was increased in HER2 amplified and TNBC, compared with luminal breast cancers, again consistent with the cell line data but was highest in the HER2-amplified tumors." (PMID 36388465, 2022). "Among these stemness-related genes, the top 3 genes positively correlated with NOLC1 were MYC, ALDH18A1, and SMAD2 in breast cancer when analyzed using the TIMER2.0 database." (PMID 35174077, 2022). "Further analyses using the GEPIA2 and TIMER2.0 databases revealed that NOLC1 was positively correlated with stemness-related genes, including MYC, ALDH18A1, ALDH1A1, SMAD2, SMAD3, etc., in both all breast cancer and TNBC." (PMID 35174077, 2022). "Moreover, the high expression of ALDH18A1 predicts a poor clinical outcome in HCC,104 NSCLC,238, 239 and breast cancer." (PMID 36694633, 2023).
Spastic paraplegia (9 papers, 2017 to 2025). Complete loss of the ability to move the lower limbs accompanied by spasticity of the lower limbs. "ALDH18A1 (located on 10q24.1) gene-related spastic paraplegias (SPG9A and SPG9B) are rare metabolic disorders caused by dominant and recessive mutations that have been found recently." (PMID 36239107, 2022). "Patients harboring mutations in the aldehyde dehydrogenase 18 family known as the member A1 (ALDH18A1) gene exhibit spastic paraplegia associated with short stature and bone dysplasia, gastroesophageal reflux, hiatal hernia, and cataracts." (PMID 30029526, 2018). "Surprisingly, heterozygous mutations in ALDH18A1 were also found in families with autosomal dominant spastic paraplegia as well as in sporadic spastic paraplegia patients (suggestive of de novo mutations)." (PMID 28653176, 2017). "Two sisters carrying a compound heterozygous variation in the ALDH18A1 gene presented with the so-far-unreported phenotype of DEE-SWAS in the context of spastic paraplegia." (PMID 38279250, 2024). "It is interesting to note that the gene for ALDH18A1 (Delta-1-Pyrroline-5-Carboxylate Synthase), a condition with symptoms comparable to those of people with PSEN1(A431E) mutation, is associated with spastic paraplegias (SPG9A and SP9B)." (PMID 37628788, 2023). "ALDH18A1 gene-related spastic paraplegias (SPG9A [spastic paraplegia-9A] and SPG9B) are rare metabolic disorders caused by dominant and recessive mutations found recently." (PMID 36239107, 2022). "The identification of ALDH18A1 as new HSP-disease gene (SPG9) pointed toward the identification of a common biochemical pathway where two other well-known IEM-disease-genes (SLC25A15 in HHH syndrome and ARG1 in Argininemia) cause syndromes where spastic paraplegia is present and highly penetrant." (PMID 30853934, 2019).
Hyperammonemia (8 papers, 2015 to 2025). An increased concentration of ammonia in the blood. "Mutation in ALDH18A1 is related to cutis laxa syndromes as well as hyperammonemia due to amino acid abnormalities." (PMID 36694633, 2023). "In ALDH18A1-related De Barsy syndrome (pyrroline-5-carboxylate synthetase deficiency, P5CSD), low levels of proline (Pro), Orn, Arg, and Cit may be found, together with mild fasting hyperammonemia." (PMID 40428324, 2025).
lung carcinoma (7 papers, 2015 to 2025). "Additionally, ALDH18A1 seems to be overexpressed in lung cancer tissues compared with normal lung tissues and is upregulated in NSCLC cell lines, A549 and the lung fibroblast cell lines, SV-80 ALDH18A1, PLOD2, and P4HA1." (PMID 37686694, 2023). "At the protein level, ALDH18A1 and CPT1B were significantly upregulated, and ACADL and PPARG were slightly underexpressed, in the lung cancer group compared to the control group, which were consistent with the results of their corresponding mRNA expressions." (PMID 34970420, 2021). "ScRNA-seq analysis of mouse PECs in lung cancer uncovered previously unknown metabolic targets in angiogenesis, specifically Serum Kinase Element (SKE) and Aldehyde Dehydrogenase 18 Family Member A1 (ALDH18A1)." (PMID 40599812, 2025). "Four differentially expressed MMRGs (ACADL, ALDH18A1, CPT1B, and PPARG) established a logistic regression model, which could effectively diagnose lung cancer." (PMID 34970420, 2021).
hereditary spastic paraplegia (6 papers, 2019 to 2025). Hereditary spastic paraplegias (HSP) comprise a genetically and clinically heterogeneous group of neurodegenerative disorders characterized by progressive spasticity and hyperreflexia of the lower limbs. "Nine mutations found in ALDH7A1 show verified association with epilepsy-related conditions, while 11 mutations found in ALDH18A1 are confirmed with hereditary spastic paraplegia." (PMID 37373306, 2023). "SPG9A and SPG9B are hereditary spastic paraplegias (HSPs) caused by dominant and recessive mutations of ALDH18A1, respectively." (PMID 33573605, 2021). "(Gln568Arg) in the ALDH18A1 gene, identified in a family with autosomal dominant hereditary spastic paraplegia (HSP)." (PMID 41342951, 2025).
neuroblastoma (6 papers, 2020 to 2025). Neuroblastoma (NB) is the most common solid, extracranial childhood tumor. "Increased ALDH18A1 in MYCN-amplified neuroblastoma is associated with amino acid and nucleotide metabolism, thus supporting the cell proliferation and self-renewal potency of cancer cells." (PMID 37835497, 2023). "The expression of ALDH18A1 was significantly associated with the overall survival of neuroblastoma patients." (PMID 36651035, 2023). "ALDH18A1 is associated with the onset and progression of neuroblastoma and may influence tumor cell proliferation and self‐renewal through a positive feedback mechanism with the MYCN gene." (PMID 39350574, 2024). "ALDH18A1 regulates neuroblastoma cell proliferation and invasiveness by modulating the proline metabolism levels." (PMID 39051546, 2024). "The engagement of MYCN in neuroblastoma metabolic rewiring was further underscored by the finding of its positive feedback loop with enzyme aldehyde dehydrogenase family 18 member A1 (ALDH18A1), a critical component in glutamine metabolism." (PMID 37835497, 2023). "Recent findings further suggest that the transcription factor myeloid zinc finger 1 (MZF1) can upregulate ALDH18A1 expression, and that elevated proline levels may contribute to the aggressive phenotype of neuroblastoma (NB) cells." (PMID 41200384, 2025). "Administration of the ALDH18A1-specific inhibitor YG1702 inhibits N-Myc expression and attenuates the growth of neuroblastoma cells." (PMID 36651035, 2023). "ALDH18A1-specific inhibitor, YG1702, inhibits MYCN expression and attenuates the growth of human neuroblastoma." (PMID 33614505, 2020). "Aldehyde dehydrogenase family 18 member A1 (ALDH18A1) is a key enzyme for the synthesis of proline from glutamate and plays important role in the proliferation, self-renewal, and tumorigenicity of neuroblastoma cells." (PMID 33614505, 2020).
autosomal dominant cutis laxa (4 papers, 2021 to 2025). Autosomal dominant cutis laxa (ADCL) is a connective tissue disorder characterized by wrinkled, redundant and sagging inelastic skin associated in some cases with internal organ involvement. "The patient was diagnosed with autosomal dominant cutis laxa with a mutation in the ALDH18A1 gene (de novo), also known as cutis laxa, autosomal dominant, type 3 (ADCL3)." (PMID 40018427, 2025). "ALDH18A1 mutations lead to delta-1-pyrroline-5-carboxylate-synthetase (P5CS) deficiency, which is a urea cycle-related disorder including SPG9A, SPG9B, autosomal dominant cutis laxa-3 (ADCL3), and autosomal recessive cutis laxa type 3A (ARCL3A)." (PMID 33573605, 2021). "Autosomal Dominant Cutis Laxa is caused by a mutation in the ELN, FBLN5, or ALDH18A1 genes." (PMID 39480826, 2024).
de Barsy syndrome (4 papers, 2019 to 2025). "ALDH18A1 pathogenic variants are responsible of De Barsy syndrome, previously known as ARCL3A, defining a molecular diagnosis that was compatible with the clinical features of patient P13." (PMID 31829210, 2019). "The use of Pro for ALDH18A1-related De Barsy syndrome is discussed in the urea cycle amino acids paragraph, together with creatine and Arg, Orn, and Cit." (PMID 40428324, 2025).